CCNB1 (cyclin B1)
Diseases named in the same sentence as CCNB1 in open-access papers (continued):
Sharing a sentence is not in itself a finding about the gene and the disease.
infection (continued). "Cyclin B1 mRNA expression was increased at day 2 (∼2.17-fold); it then decreased to the baseline from day30 to 360 post-infection." (PMID 22253905, 2012). "We observed a reversal of the infection-induced cyclin B1 kinetics in UHRF1 knock-down cells." (PMID 31492965, 2020). "We hypothesized that these interactions with histone deacetylases and methyltransferases might affect the histone marks on the CCNB1 promoter in the course of infection." (PMID 31492965, 2020). "We observed enhanced UHRF1 binding to the CCNB1 promoter at 3 h of infection." (PMID 31492965, 2020). "Our results showed that after infection, dissipation of BubR1 was observed before the culminating of cyclin B1 level, whereas dissipation of MAD2 was lagged and moderate, suggesting that SAC could not be sustainably activated." (PMID 29520102, 2018). "At early times during MVM infection, prior to the loss of cyclin B1, we have shown that the complex was inactive due to the inhibitory phosphorylation of CDK1 (lanes 1 and 2), thus, we expected that at these times cyclin B1 would remain cytoplasmic." (PMID 24415942, 2014). "Depletion of cyclin B1 mRNA, however, occurred as early as 24 h after infection." (PMID 24415942, 2014). "Until day180, i.e. in the early and middle stages of infection, gene expression level of CyclinA was increased in a time-dependent manner, while gene expression levels of Cyclin B1 and CyclinD1 were increased up to day30 and then returned to the control level after day60." (PMID 22253905, 2012). "Importantly, the kinase activity of the cyclin B1/CDK1 complex in MVM infected cells is significantly reduced, suggesting that the loss of this activity plays a key role in maintaining the pre-mitotic cell cycle block during MVM infection." (PMID 29088070, 2017). "It is not known whether mis-localization of cyclin B1 at early times during infection is a necessary prelude to its eventual loss." (PMID 24415942, 2014). "However, surprisingly, at 24 h post MVM infection, when 70–80% of cells were infected, we observed that the cyclin B1 that was present displayed a nuclear localization in approximately 90% of infected cells, and in many cells showed co-localization with MVM NS1 in APAR replication centers." (PMID 24415942, 2014). "In cultured VSMCs, treatment with PGE1-OH or infection of Ad-EP4 also significantly upregulated the mRNA levels of genes related to cell proliferation including Ki67, Foxm1, Ccna2, Ccnb1, Ccnd1, Ccnd2, Ccne1, and CDK2." (PMID 36078128, 2022). "This analysis revealed that STAT3 itself, and its targets such as CCNB1 and CCND1, were significantly downregulated in Hs 578T and MDA-MB-231 TNBC cells following shNONO infection." (PMID 32724453, 2020). "Our results showed that at early stages (infection after 0–3.5 days), upregulation of mitosis markers p-CDC2 (T161), CDC2, cyclin B1, and p-Aurora A (T288)/Aurora B (T232) was observed in U87 cells, but not in U251 cells." (PMID 29520102, 2018). "This suggests that a unique interaction with the cell cycle machinery during infection mediated by viral replication and the DDR triggers Ccnb1 inhibition." (PMID 29088070, 2017). "While the Y15 phosphorylation of CDK1 that normally inhibits entry into mitosis was lost as infection progressed, the MVM induced DDR resulted in the near-complete depletion of cyclin B1, thus directly inhibiting cyclin B1-CDK1 complex function." (PMID 24415942, 2014). "Nuclear localization of cyclin B1 implies that the infection-imposed G2/M block, represented by a cytoplasmic localization of cyclin B1, is not fully maintained at the late stages of infection." (PMID 36568985, 2022). "Infection with RHΔROP16 parasites did not result in decreased cyclin B1 expression, in contrast to the RH WT strain." (PMID 31492965, 2020). "Cyclin B1 was about three and five times higher in VV-infected cells in comparison with nontreated cells, for 24 h and 48 h of infection, respectively." (PMID 28951871, 2017).
infection (continued). "Additionally, retro-miR-150 infection of mir-150−/− CD8+ T cells reduced expression of anergy-related genes Cbl-b, Egr2, and p27 and increased the expression of activation-induced molecules granzyme B, cyclin B1, and Blimp1 following anti-CD3/CD28 stimulation." (PMID 28572627, 2017). "It is not yet clear whether the mis-localization of cyclin B1 at early times during infection is a necessary step in its subsequent depletion." (PMID 24415942, 2014). "We assume that depletion of cyclin B1 is also a necessary feature of MVM infection; however, how reduced cyclin B1 levels facilitate infection is not yet clear." (PMID 24415942, 2014).
adenocarcinoma (7 papers, 2010 to 2023). A common cancer characterized by the presence of malignant glandular cells. "We transfected the corresponding saRNAs into NIH/3T3 and transgenic adenocarcinoma mouse prostate (TRAMP) C1 cells and identified two saRNAs (dsCcnb1–313 and dsCcnb1–597) that elevated Ccnb1 mRNA expression levels." (PMID 20107511, 2010).
musculoskeletal diseases (1 paper, 2024). "SMAD7 shows the strongest association with musculoskeletal diseases, with CCNB1 in second place." (PMID 39840278, 2024).
neurodegenerative disease (1 paper, 2014). A disorder of the central nervous system characterized by gradual and progressive loss of neural tissue and neurologic function. "Stimulation of N-methyl-d-aspartate receptors that occurs in neurodegenerative diseases promoted the accumulation of cyclin B1 in the nuclei of cortical neurons, which led the neurons to undergo apoptotic death." (PMID 24444371, 2014).
CCNB1 also shares sentences with these, for which no sentence is quoted: renal clear cell carcinoma (4 papers); myocardial infarction (3); ductal adenocarcinoma (2); leiomyosarcoma (2); liver cirrhosis (2); lung squamous cell carcinoma (2); malaria (2); renal cell carcinoma (2); acute kidney injury (1); adenoid cystic carcinoma (1); allergic asthma (1); aristolochic acid nephropathy (1); astrocytomas (1); atherosclerosis (1); atopic eczema (1); autoimmune disease (1); benign breast tumors (1); bile duct cancer (1); Bloom syndrome (1); brain ischemia (1); breast disease (1); cardiac embolism (1); chlamydial infection (1); cholangiocarcinoma (1); chronic lymphocytic leukemia (1); colorectal NETs (1); cystadenoma (1); dengue fever (1); Dengue hemorrhagic fever (1); dental caries (1).
A further 49 diseases each share a sentence with CCNB1 in 1 paper.